MC4R (melanocortin 4 receptor)
Diseases named in the same sentence as MC4R in open-access papers (continued):
Sharing a sentence is not in itself a finding about the gene and the disease.
Obesity (continued). "Furthermore, loss-of-function genetic variants of MC4R are associated with obesity whereas gain-of-function genetic variants are protective against obesity." (PMID 32733386, 2020). "Activation of type 4melanocortin receptors (MC4R) in the hypothalamic neuronsreduces food consumption and increases energy expenditure,while their blockade or loss (knockout) is associated withhyperphagia,gradual development of obesity, and insulinresistance." (PMID 33659800, 2020). "The MC4R rs17782313 SNP has also been linked with obesity in Europeans and Koreans." (PMID 32807123, 2020). "A recent genomic association study conducted within the European population revealed 61 non-synonymous variants in MC4R, of which 77% produce a decreased level of MC4R that is insufficient to bind to β-arrestin-2 and increases BMI and risks of obesity and T2DM." (PMID 31947684, 2020). "Our case-control study does reveal that rs17782313 in MC4R associates with obesity at p=3x10-4." (PMID 31888951, 2020). "Besides increased fat mass, they also have more lean mass, greater bone-mineral density, and are taller compared with non-MC4R deficient individuals with obesity." (PMID 32692746, 2020). "POMC and MSH deficiencies, as well as MC4R deficiencies/mutations or pharmacological blockade of MC4R have been linked to hyperphagia and obesity, increased lipid up-take, triglyceride synthesis and fat accumulation in white adipose tissue in animals and humans." (PMID 32369484, 2020). "We show that the obesity-increasing effect of MC4R mutations may be mitigated by a low overall genetic susceptibility to obesity." (PMID 32692746, 2020). "However, this study demonstrated the strong association between the C allele at the rs17782313 polymorphic locus of the MC4R gene and obesity, hypertension, and elevated plasma levels of DNAJC27." (PMID 32733386, 2020). "A study also demonstrated that genetic variants in MC4R affect the obesity phenotype in Koreans." (PMID 32807123, 2020). "A meta-analysis has revealed that the genes of pharmacodynamic targets of antipsychotics like HTR2C, DRD2, ADRA2A and genes implicated in obesity such as MC4R, GNB3, FTO, LEP, LEPR, BDNF, and INSIG2 seem to be consistently relevant to antipsychotic-induced weight gain." (PMID 32116676, 2019). "Mutations of MC4R are known to cause a monogenic form of obesity in humans via leptin." (PMID 31852448, 2019). "Moreover, the constructed haplotype ACAC of four SNPs of the MC4R gene (rs2331841, rs6567160, rs571312, and rs17782313) was significantly associated with obesity." (PMID 31781208, 2019). "Here, by measuring the functional consequences of all missense MC4R variants in cells, we demonstrate strong associations for GoF variants with lower risk of obesity and show that LoF variants are associated with obesity and diabetes risk in the general population." (PMID 31002796, 2019). "Generally, mutations in leptin (LEP), the leptin receptor (LEPR) and the melanocortin 4 receptor (MC4R) represent the most common cause of monogenic forms of obesity and mutations within these genes have been demonstrated to cause childhood morbid obesity in probands of various ethnicities." (PMID 31488071, 2019). "In conclusion, deficient activation of MC4R by α-MSH/IgG IC may contribute to the pathophysiology of hyperphagic obesity as a result of low level and altered binding properties of α-MSH-reactive IgG in OB patients." (PMID 30755592, 2019). "Moreover, recent studies found that the SNPs rs12970134, rs17782313, rs571312, rs2331841, rs6567160, and rs11872992 in the MC4R gene were associated with obesity or obesity-related parameters." (PMID 31781208, 2019). "The melanocortin 4 receptor (MC4R) is a G protein-coupled receptor whose disruption causes obesity." (PMID 31002796, 2019).
Obesity (continued). "By combining genetic studies in over 0.5 million people with detailed functional characterization of identified MC4R variants in cells, we demonstrated that β-arrestin-biased GoF MC4R variants are associated with lower risk of obesity and its cardio-metabolic complications in the general population." (PMID 31002796, 2019). "Harnessing β-arrestin-biased MC4R signaling may represent an effective strategy for weight loss and the treatment of obesity-related cardiometabolic diseases." (PMID 31002796, 2019). "Therefore, in the present study, we aimed to investigate the association of SNPs of the MC4R gene with metabolically healthy and unhealthy obesity in Chinese Northern Han populations." (PMID 31781208, 2019). "To date, inactivating MC4R mutations are the most frequent monogenic cause of obesity." (PMID 31417496, 2019). "Of note, the most common monogenic form of obesity in humans is due to mutations in MC4R." (PMID 31067764, 2019). "These alleles were anticipated as global risk alleles for MC4R variants in obesity." (PMID 31429705, 2019). "A recent study published in Science safely targeted the non-coding genomic region of Sim1 and MC4R with rAAV packed with CRISPRa, and successfully rescued the obesity syndrome caused by haploinsufficiency in a murine model, which shed light on their potential therapeutic applications in the future." (PMID 31124015, 2019). "Therefore, the MC4R rs17782313 gene polymorphisms was associated in certain studies with obesity in both adults and children." (PMID 31350533, 2019). "Additionally, we found previously known mutations in the MC4R gene in four patients, thus monogenic obesity prevalence was 10.4% in our cohort." (PMID 30991789, 2019). "Thus, in this study we aimed to determine the association between MC4R gene variants (rs12970134 and rs17782313) because these are risk factors in obesity; and different clinical characteristics of PCOS." (PMID 31429705, 2019). "Thus, we believe that the main cause of obesity and fat deposit in agouti-mice is a decrease in the rate of energy metabolism, as result of the weakening of hypothalamic MC4R-signaling." (PMID 30870482, 2019). "Polymorphisms in FTO and MC4R have been associated with obesity in children." (PMID 31354816, 2019). "Therefore, we aimed to study single nucleotide polymorphisms (SNPs) in the MC4R gene associated with metabolically healthy and unhealthy obesity in Chinese Northern Han populations." (PMID 31781208, 2019). "Hence, to assess the effect of SDV as a preventative measure for Mc4r−/− deficient obesity, mice were assigned to three groups." (PMID 29545738, 2018). "Variants in the MC4R gene represent the most common cause of monogenic obesity." (PMID 29880780, 2018). "Indeed, genetic variation in MC4R, which encodes the melanocortin 4 receptor, strongly influences obesity risk at a population level." (PMID 29691411, 2018). "Eight-weeks of voluntary exercise has been shown to prevent obesity, hyperphagia, hyperleptinemia and glucose intolerance in young MC4R knockout mice; paradoxically, this effect was associated with increased NPY and decreased POMC and MC3R expression in arcuate nuclei." (PMID 29867590, 2018). "Interestingly, 4 of the 120 Bedouin controls were heterozygous for the c.307G > A p.V103I MC4R variant previously associated with protection from obesity (ExAC frequency for this variant is 0.01743)." (PMID 30068297, 2018). "By contrast, the MC4R variant rs2229616 is negatively associated with obesity." (PMID 29679223, 2018). "The disruptions of POMC or MC4R in humans have been linked to early onset obesity." (PMID 29598821, 2018). "While it has been suggested that obesity due to MC4R mutations can be caused by either haplo-insufficiency or dominant negative activity exerted by the mutant receptor, co-transfection studies show that the extreme majority of mutations analyzed do not have dominant negative activity." (PMID 30068297, 2018).
Obesity (continued). "There has been a postulation that genetic alteration like the common single-nucleotide polymorphism variants around the melanocortin 4 receptor gene could be associated with the co-occurrence of obesity and CRA." (PMID 29288474, 2018). "We examined whether CANA inhibits the development of insulin resistance- and obesity-associated metabolic phenotypes in MC4R-KO mice on a WD feeding regimen." (PMID 29402900, 2018). "Furthermore, eQTL and meQTL results strongly indicate that obesity-associated rs17782313 T allele was significantly associated with promoter hypermethylation and decreased expression of MC4R, thus involved in the childhood obesity." (PMID 27926527, 2017). "The underlying loci of these two SNPs, FTO and MC4R, are well established obesity-related loci." (PMID 28448539, 2017). "Therefore, the Mc4r-deficient mice more closely reflect energy supply-driven obesity and allow studying hepatic changes found in NAFLD but leaving the leptin system genetically intact." (PMID 28207798, 2017). "However, Xi and colleague found that the association between the MC4R rs17782313 and obesity was influenced by sedentary behaviors and physical activity in Chinese children." (PMID 28081251, 2017). "Importantly, multiple meta-analyses and GWAS studies have confirmed the association between Mc4r polymorphisms and obesity and its associated comorbidities." (PMID 28930194, 2017). "Indeed, both Pomc/POMC-deficient mice and humans develop hyperphagia and obesity, and genetic deletion of Mc4r/MC4R in mice and humans results in severe hyperphagic obesity." (PMID 28013339, 2017). "The data suggested the unhealthy lifestyle strengthen the contribution of MC4R variant to obesity." (PMID 28081251, 2017). "Rare functional mutations in MC4R are known to develop childhood-onset obesity." (PMID 27926527, 2017). "In humans, mutations of MC4R are the most frequent monogenic cause of severe early-onset obesity." (PMID 28207798, 2017). "Gene-environment interactions might influence the effect of MC4R variants on obesity, which was still unclear." (PMID 28081251, 2017). "In 1998, two groups reported the first functionally relevant MC4R mutations for obesity." (PMID 28615046, 2017). "Melanocortin-4 receptor (Mc4r)-deficient mouse models exhibit obesity during adulthood." (PMID 28930194, 2017). "Nevertheless, recent GWAS have identified SNPs in the MC4R 3′ UTR region to have a strong association with obesity, with rs17782313 showing the second strongest association signal after FTO and rs129070134 showing association not just in Caucasian populations but also in Asian populations." (PMID 28615046, 2017). "Melanocortin-4 receptor (MC4R) mutations are the most common known cause of monogenic obesity." (PMID 28218067, 2017). "We may hypothesize that the molecular mechanisms affecting obesity and the associated liver fat accumulation and damage may be common for maternal-associated programming of obesity and for Mc4r pathways." (PMID 28930194, 2017). "Earlier GWAS has identified that rs17782313 near MC4R was associated with obesity." (PMID 27926527, 2017). "As a result, studying the animal model of the syndrome may help scientists better understand why mutations in the gene for the melanocortin-4 receptor cause obesity and how to better care for people with these mutations." (PMID 28829041, 2017). "Diseases associated with ADRB3 include obesity based on MC4R deficiency." (PMID 27147943, 2016). "An association between MC4R rs17782313 and obesity has been reported in a European population." (PMID 27213003, 2016). "Other genes associated with obesity have since been reported, including the melanocortin-4 receptor (MC4R), adiponectin, C1Q and collagen domain containing, brain-derived neurotrophic factor, leptin, peroxisome proliferator-activated receptor gamma-2 and SH2B1 genes." (PMID 27213003, 2016).
Obesity (continued). "In particular, MC4-R mutations result in a severely obese phenotype and may be responsible for up to 4% of all cases of severe obesity in certain populations." (PMID 26758700, 2016). "MC4R knockout or loss-of-function variants in humans result in hyperphagia and early onset obesity." (PMID 27551276, 2016). "The interactions of mental stress and energy intakes with the MC4R minor allele genotype might be associated with increased risk of obesity in Korean adults." (PMID 27213003, 2016). "Therefore, we investigated the interaction of MC4R variants and dietary patterns on the risk of obesity in Korean middle-aged adults." (PMID 27213003, 2016). "Mutations in Mc4r are the most frequent monogenic cause of severe early-onset obesity in humans." (PMID 28030540, 2016). "The effect of MC4R deficiency on obesity and metabolism homeostasis is fairly consistent." (PMID 27713523, 2016). "However, there was a significant association between obesity and fat intake and MC4R genotypes when fat intake was higher than 14 % of energy, which was the median of these cohorts." (PMID 27213003, 2016). "Morbid obesity is associated with silencing of MC4R activation." (PMID 27147943, 2016). "It has also been reported that MC4R variants are associated with the incidence of obesity." (PMID 27213003, 2016). "Therefore, as was done for the patient in this case report, all patients with MC4R mutations should be advised that lifestyle modification can oppose the obesity effect from MC4-R deficiency." (PMID 27738543, 2016). "This case links the 18q deletion to a MC4-R deficiency phenotype of obesity." (PMID 27738543, 2016). "The prevalence of obesity is on the increase in South Africa, and it is hypothesized that mutations in MC4R are a contributing factor." (PMID 26788538, 2016). "There was a significant and relevant interaction between mental stress levels and MC4R polymorphism when determining the risk of obesity after adjusting for confounders such as age, gender, area, daily energy intake, total activity and smoking status (P = 0.0359)." (PMID 27213003, 2016). "Those previous studies found that the MC4R rs17782313 C allele was a risk allele for obesity." (PMID 27213003, 2016). "Similarly, Mc4r deficiency leads to obesity but had only small effects on plasma lipid levels and no atherosclerotic plaques were found on standard chow and semisynthetic diet." (PMID 28030540, 2016). "We hypothesized that there is an interaction between MC4R rs17782313 variants and diet and lifestyle that influence the risk of obesity." (PMID 27213003, 2016). "Furthermore, the injection of agonists of the MC4-R ICV into mice significantly depresses food consumption while chronic blockade of MC4-R causes obesity." (PMID 27942392, 2016). "Because MC4R is involved in eating behavior and stress and MC4R variants are associated with obesity, MC4R variants may modulate energy balance via gene-nutrient interactions." (PMID 27213003, 2016). "Mutations in MC4-R have been shown to play a major role in the genetics of obesity." (PMID 26758700, 2016). "The decrease in α-MSH and increase in AGRP, and subsequent sustained repression of MC4R, result in increased food intake, which may cause obesity." (PMID 27213003, 2016). "To investigate this, we determined the interaction between the MC4R variant rs17782313 and both nutrient intake and mental stress in the development of overweight and obesity among 8842 Korea adults over 40 years of age from the Korean Genome Epidemiology Study (KoGES) study." (PMID 27213003, 2016). "Thus, the mutation of the Mc4r gene is thought to be responsible for obesity in the Obese-10 pedigree." (PMID 27585985, 2016). "In addition to obesity, MC4R deficient children display hyperinsulinemia and increased linear growth." (PMID 25825681, 2015). "However, smoking has been implicated in appetite suppression through the POMC neural pathway, and loci in this pathway (POMC and MC4R) increase obesity risk." (PMID 26537541, 2015).
Obesity (continued). "Our results suggest MC4R obesity risk variants might mitigate the appetite suppressant effect of nicotine in adolescent female smokers." (PMID 26537541, 2015). "Likewise, humans with MC4R mutations develop obesity, and in severe, early onset childhood obesity, the frequency of mutations in the MC4R locus causing decreased functionality is 4–6 %." (PMID 26459134, 2015). "Additionally, the MC4R gene is the most common genetic cause of human obesity in inherited morbid obesity." (PMID 26032905, 2015). "rs17782313, located 188 kb downstream of MC4R, was similarly associated with obesity." (PMID 26032905, 2015). "Both BDNF and MC4R have previously been shown to be associated with obesity in other populations." (PMID 25760438, 2015). "Inactivating mutations in MC4R are the single most common form of monogenic obesity in humans." (PMID 26113808, 2015). "While the loss of the MC4R gene is a probable cause of obesity in the affected cases, the presence of horseshoe kidney in our Case 2 may also be associated with this loss." (PMID 24637311, 2014). "For example, extreme obesity can be due to mutations in genes such as MC4R." (PMID 24705671, 2014). "Mutation in MC4R is the most common single known cause of monogenic obesity." (PMID 25093408, 2014). "Examining the effects of MC4R rare variants in weight-loss after surgery by matching subjects for other variables minimizes confounding factors that cannot be eliminated or addressed in population studies of obesity." (PMID 24705671, 2014). "Rare mutations in the MC4R coding region account for a significant number of severe obesity cases." (PMID 24820477, 2014). "Therefore, in the current study, we investigate the relative contribution of common variation across MC4R on risk of obesity in American Indians, and further explore the effect of common MC4R variation on energy intake and energy expenditure measures." (PMID 25103139, 2014). "Moreover, a promoter variant rs11872992 in MC4R influences risk of obesity, perhaps in part through a propensity for increased food intake and decreased energy expenditure." (PMID 25103139, 2014). "However, a smaller study of MC4R in a Belgian case/control study (1,049 obese/312 control) reported that a promoter SNP rs11872992 was associated with obesity (p = 0.03), and this signal was independent from rs17782313." (PMID 25103139, 2014). "In addition to variants within the MC4R coding region, common variants outside of the coding region have been associated with common and severe forms of obesity." (PMID 24820477, 2014). "Since many MC4R variants have unknown defects, the analysis of each mutation to determine the in vitro signaling defects and their possible correlation with obesity phenotypes is necessary." (PMID 24705671, 2014). "Mutations in MC4R are the most common cause of monogenic obesity in humans." (PMID 25337124, 2014). "This raises the possibility that different variants in MC4R may contribute to obesity in American Indians." (PMID 25103139, 2014). "Moreover, the reduction in heart rate and dissociation between obesity and hypertension has been found in humans, suggesting that the rat model retains clinically relevant features of MC4R deficiency." (PMID 24400148, 2013). "Notably, mutations in the MC4R gene are the most common monogenic disorders that cause obesity in humans." (PMID 23543895, 2013). "The MCR gene family consists of five members and two of them (MC3R and MC4R) are involved in the control of mammalian energy homeostasis and thus their mutations and polymorphisms may predispose to obesity." (PMID 24142065, 2013). "Individuals with mutations in MC4R gene have lower blood pressure (BP), independently of obesity." (PMID 23849767, 2013). "In addition, 7 of the 17 (41.2%) GWAs-selected genes (FTO, TMEM18, INSIG2, FAIM2/BCDIN3, BDNF, SH2B1 and MC4R) were associated with obesity in this population." (PMID 23950976, 2013).